ABCB1 (ATP binding cassette subfamily B member 1)
Diseases named in the same sentence as ABCB1 in open-access papers (continued):
Sharing a sentence is not in itself a finding about the gene and the disease.
parasitemia (2 papers, 2017 to 2024). "The present study also showed the association of ABCB1 gene haplotypes on parasitemia clearance rate over treatment time." (PMID 28975866, 2017). "ABCB1 and SLCO2B1 genes were associated with the clearance rate over treatment time in the model adjusting for age, gender, co-medication, parasitemia baseline level and genetic ancestry." (PMID 28975866, 2017). "After FDR procedure, ABCB1 gene was no longer associated with parasitemia clearance rate over treatment time." (PMID 28975866, 2017). "Mean parasitemia over treatment time according to ABCB1 and SLCO2B1 genes." (PMID 28975866, 2017).
prostate adenocarcinoma (2 papers, 2021 to 2024). "We also analyzed ABCB1 levels relative to the therapy outcome (Prostate Adenocarcinoma, TCGA, Firehose Legacy)." (PMID 39090086, 2024).
resistant cancer (2 papers, 2017 to 2021). "In taxane-resistant cancer, ABCB1 (encoding multidrug resistance protein 1; MDR1 or P-glycoprotein) and ABCG2 (encoding breast cancer resistance protein; BCRP) ABC transporters have been studied well as transporters of paclitaxel in several carcinomas." (PMID 34503223, 2021).
respiratory depression (2 papers, 2024 to 2025). A decrease in ventilation secondary to impaired signals from the central nervous system. "In this study, children with the ABCB1 rs9282564 GG and GA genotypes had an increased risk of respiratory depression and prolonged hospitalisation." (PMID 41009999, 2025).
septal defects (2 papers, 2013 to 2018). "Finally, a Han Chinese study found that although maternal occupational exposure to various persistent organic pollutants was associated with a higher incidence of CHDs, infants carrying the ABCB1 gene C3435T polymorphism were at greater risk, particularly for septal defects." (PMID 30257432, 2018). "The C3435T polymorphism in the ABCB1 gene of fetus increases the risks of CHD in a Han Chinese population when the mothers are exposed to phthalates and alkylphenolic compounds during the periconceptional period, particularly for septal defects." (PMID 23874772, 2013).
serous adenocarcinoma (2 papers, 2016 to 2024). An adenocarcinoma that is characterized by the presence of papillary patterns and cellular budding. "Two studies illustrated the ability of UCA1 to induce PTX resistance in SKOV3 and high-grade serous adenocarcinoma HeyA8 cells by regulating the expression of two miRNAs and their target genes: miR-129/ABCB1 and miR-654-5p/SIK, respectively." (PMID 38534790, 2024).
steatosis (2 papers, 2018 to 2021). Increased lipid within the cytoplasm of cells. "P-glycoprotein (Pgp, MDR1—multidrug resistance protein 1, ABCB1—ATP-binding cassette sub-family B member 1), encoded by the ABCB1 gene, is another membrane protein implicated in lipid homeostasis and steatosis." (PMID 33557317, 2021).
systemic sclerosis (2 papers, 2018 to 2021). A chronic disorder, possibly autoimmune, marked by excessive production of collagen which results in hardening and thickening of body tissues. "A haplotype analysis of ABCB1, which had been conducted in patients with systemic sclerosis (SSc) in Poland, revealed a statistically significantly higher frequency of the 1236C-2677G-3435T haplotype in the SSc group in comparison with the control group (25 vs. 15%, p = 0.032)." (PMID 29948283, 2018).
thromboembolic disease (2 papers, 2023). "Several studies have investigated the effect of ABCB1 polymorphisms on RIVA concentration, bleeding, and thromboembolism events." (PMID 36827667, 2023).
uterine corpus endometrial carcinoma (2 papers, 2020 to 2024). A endometrial carcinoma (disease) that involves the body of uterus. "Out of these, mutations observed in uterine corpus endometrial carcinoma were taken into account for further analysis, which narrowed down to a total of 248 mutations: 118 in ABCB1, 82 in ABCC1, and 48 in ABCG2." (PMID 38766631, 2024). "For example, ABCB1 mutational frequency was as much as 13.2% in 530 cases of uterine corpus endometrial carcinoma in the TCGA-UCEC project." (PMID 34541464, 2020).
acute GVHD (1 paper, 2025). "They identified that wild-type genotypes for the rs4148732 and rs6950978 polymorphisms of the ABCB1 gene are associated with a lower competitive risk of death before the development of acute GVHD." (PMID 40740999, 2025).
alopecia (1 paper, 2025). Hair loss usually from the scalp. "For the ABCB1 gene, fatigue severity significantly increased after cycles one and two, while alopecia severity increased after all chemotherapy cycles among patients carrying the GG genotype (p < 0.05)." (PMID 40283974, 2025).
Anxiety and Depression (1 paper, 2022). "Moreover, the Swiss Society for Anxiety and Depression (SGAD) recommends genotyping of the P-glycoprotein (P-gp, encoded by ABCB1) after antidepressant treatment failure." (PMID 35911243, 2022).
asthenia (1 paper, 2023). Clinical sign or symptom manifested as debility, or lack or loss of strength and energy. "Likewise, the association between ABCB1 rs203258 G/T and asthenia can only be explained as a spurious event because a heterozygous disadvantage is not possible for traits inherited in a codominant manner." (PMID 36817149, 2023). "Furthermore, the incidence of asthenia was 20% in individuals with ABCB1 rs203258 G/T genotype, 8.3% in those with A/A and 0% for those with G/G, G/A, T/T o A/T genotypes (p = 0.013)." (PMID 36817149, 2023).
astrocytoma (1 paper, 2022). "Only single studies have analyzed the DNA promoter methylation of ABCB1 in GBM patients, and the data concerning other tumors of a glial origin, including astrocytoma or oligodendroglioma, are scarce." (PMID 36233525, 2022).
Ataxia (1 paper, 2022). Ataxia refers to impaired coordination of voluntary muscle movement. "Dogs homozygous for the ABCB1-1Δ variant and thus without functional P-glycoproteins exhibit neurotoxic symptoms such as ataxia, lethargy, coma, tremors, seizures, mydriasis, and blindness at ivermectin doses that are not toxic for wildtype dogs." (PMID 36037240, 2022).
biliary atresia (1 paper, 2020). A rare, biliary tract disease characterized by progressive obliterative cholangiopathy of the intra- and extrahepatic bile ducts, occurring in the embryonic/ perinatal period, leading to severe and persistent neonatal jaundice and acholic stool. "Notably, ABCG2 and ABCC4 are almost absent in controls but abundant in biliary atresia; ABCB1 and ABCB4 are both significantly upregulated to the point that ABCB4 is the most abundant transporter in BA Livers, overtaking ABCD3." (PMID 33128234, 2020).
cerebral amyloid angiopathy (1 paper, 2017). "The authors showed that the absence of ABCB1 results in a significant disturbance of Aβ removal in a transgenic murine model of AD (APP/PS1+/−−ABCB1), leading to an increased intraparenchymal cerebral amyloid angiopathy." (PMID 29317984, 2017).
cerebral infarction (1 paper, 2024). An ischemic condition of the brain, producing a persistent focal neurological deficit in the area of distribution of the cerebral arteries. "This study investigated the relationship between ATP-binding cassette sub-family B member 1 (ABCB1) and OLIG2 single nucleotide polymorphism (SNP) and neurological injury severity and outcome in cerebral infarction (CI)." (PMID 38221931, 2024).
colorectal adenoma (1 paper, 2019). An adenoma that arises from the colon or rectum. "In human colonic tissue sections, ABCB1 was highly polarised to apical brush border membranes in normal colonic crypts and also in the neoplastic glands of differentiated colorectal adenomas, colocalising with F‐actin." (PMID 30306567, 2019).
cutaneous T-cell lymphoma (1 paper, 2023). "The polymorphism in ABCB1 exon 21 was found to be a genetic factor associated with cutaneous T-cell lymphoma." (PMID 38004402, 2023).
dilated cardiomyopathy (1 paper, 2025). Cardiomyopathy which is characterized by dilation and contractile dysfunction of the left and right ventricles. "In this study, bioinformatics analyses and multiomics techniques were employed to elucidate the molecular mechanisms underlying dilated cardiomyopathy (DCM) and to identify five potential biomarkers: VCL, ABCB1, JAK2, KDR, and NGF." (PMID 40217309, 2025).
Dystonia (1 paper, 2021). An abnormally increased muscular tone that causes fixed abnormal postures. "Polymorphism in a p-glycoprotein transporter gene, ATP-binding cassette sub-family B member 1 (ABCB1), was only marginally associated with dystonia and akathisia." (PMID 34209185, 2021).
familial Mediterranean fever (1 paper, 2025). Familial Mediterranean fever (FMF) is an autoinflammatory disorder characterized by recurrent short episodes of fever and serositis resulting in pain in the abdomen, chest, joints and muscles. "Association of drug transporter gene ABCB1 (MDR1) 3435C to T polymorphism with colchicine response in familial Mediterranean fever." (PMID 39912853, 2025).
fragile X syndrome (1 paper, 2024). A genetic syndrome caused by mutations in the FMR1 gene which is responsible for the expression of the fragile X mental retardation 1 protein. "These genes include ATP Binding Cassette Subfamily B Member 1 (ABCB1) and Thrombospondin-1 (THBS1), as well as the fragile X messenger ribonucleoprotein 1 (FMR1) gene in Fragile X Syndrome to induce transcriptional repression." (PMID 39108836, 2024).
gastric diseases (1 paper, 2020). "Other SNPs in the ABCB1 gene has been shown to be associated with gastric diseases." (PMID 31948121, 2020).
gastric ulcer (1 paper, 2025). An ulcerated lesion in the mucosal surface of the stomach. "The results showed that the levels of ABCB1, ALOX5, NF-κB, and Caspase9 were significantly increased in the mice with gastric ulcers in the model group, but pretreatment with the CHRs reduced these expressions in a dose-dependent manner." (PMID 40283949, 2025). "To further explore the underlying anti-inflammatory and anti-apoptotic molecular mechanisms of the CHRs, we performed IHC to detect the levels of ABCB1, ALOX5, NF-κB, Caspase9, and Bcl-2 in the stomach tissue of the mice with gastric ulcers." (PMID 40283949, 2025).
glaucoma (1 paper, 2022). Increased pressure in the eyeball due to obstruction of the outflow of aqueous humor. "To date, the response to latanoprost of patients with glaucoma and ocular hypertension, is reported to be associated with the genetic polymorphism of seven genes (ABCB1, SLCO2A1, AFAP1, GMDS, PTGS1, MRP4, and PTGFR)." (PMID 36313286, 2022). "Rs1045642 in ABCB1, rs4241366 in SLCO2A1, rs9503012 in GMDS, rs10306114 in PTGS1, rs11568658 in MRP4, rs10786455 and rs6686438 in PTGFR were reported to be positive with the response to prostaglandin analogs in patients with glaucoma." (PMID 36313286, 2022).
glomerulonephritis (1 paper, 2014). A renal disorder characterized by damage in the glomeruli. "The relative order of magnitude in transcript expression for glomerulonephritis patients was ABCC2>SLCO1A2>ABCB1 = ABCG2 for SLE and SLCO1A2>ABCC2>ABCB1>ABCG2 for SVV." (PMID 24548980, 2014). "Our studies demonstrated reasonable leukocyte expression of transporter transcripts (ABCC2, ABCB1, ABCG2; 90% of patients and SLCO1A2; 50% of patients) in the blood of glomerulonephritis patients." (PMID 24548980, 2014).
heart transplant (1 paper, 2022). "In study of 170 heart transplant recipients, the ABCB1 3435CC genotype was associated with an increased risk of rejection." (PMID 36432633, 2022).
hemangiosarcoma (1 paper, 2014). "Our results suggest that ABCB1 and ABCG2 expression might contribute to the higher doxorubicin resistance observed for the hemangiosarcoma CSF-1Rhigh cell populations; however, other transporters or mechanisms appear to be involved in drug resistance in the AS5 cell line." (PMID 25295160, 2014).
kidney tumors (1 paper, 2025). "In pancreatic and kidney tumors, high expression of ABCB1 is a favorable prognostic factor." (PMID 41426972, 2025).
leiomyoma (1 paper, 2023). A well-circumscribed benign smooth muscle neoplasm characterized by the presence of spindle cells with cigar-shaped nuclei, interlacing fascicles, and a whorled pattern. "The involvement of many proteins such as FN1, COL1A1, BMP7, CCND1, EZH2, HMGA2, AhR, and E2F1 shown in the protein–protein interaction networks are well known in leiomyoma pathogenesis; others, such as SOX2, REN, PPARG, ABCB1, and NR3C1 are novel and require further investigation." (PMID 36835153, 2023).
lipid metabolism disorders (1 paper, 2011). "Interestingly, in favour of a role for Pgp in lipid metabolism in humans, single nucleotide polymorphisms on the Pgp coding gene ABCB1 have been associated with lipid metabolism disorders in several independent studies." (PMID 21949682, 2011).
lymphoid tumor (1 paper, 2015). "In this study, we revealed that DNA methylation and histone acetylation within the promoter region of the ABCB1 gene were associated with the regulations of its expression in canine lymphoid tumor cell lines." (PMID 29061940, 2015). "In veterinary medicine, we previously examined the epigenetic regulations of the ABCB1 gene in canine lymphoid tumor cell lines." (PMID 29061940, 2015).
malignant glioma (1 paper, 2024). A grade III or grade IV glioma arising from the central nervous system. "Both endothelial cells and malignant glioma cells have been reported to express high levels of ABC transporters, specifically P-glycoprotein (P-gp) (encoded by the—ABCB1 gene), ABCG2 and ABCC4." (PMID 38589905, 2024).
malignant mesothelioma (1 paper, 2023). A malignant neoplasm of the pleura or peritoneum, arising from mesothelial cells. "One study has reported that mitochondrial ABCB1 (ATP binding cassette subfamily B member 1, also known as multidrug protein 1) plays a key role in the chemoresistance to metformin in human malignant mesothelioma." (PMID 37239373, 2023).
malignant peripheral nerve sheath tumor (1 paper, 2022). Malignant peripheral nerve sheath tumor (MPNST) is a rare and often aggressive soft tissue sarcoma occurring in a wide range of anatomical sites. "In particular, ABCB1 and ABCC3 activation and an increase in corresponding protein levels associated with pour prognosis were shown in malignant peripheral nerve sheath tumor (MPNST)." (PMID 35328603, 2022).
mood disorder (1 paper, 2023). A cognitive disorder a disturbance in which the person's mood is hypothesized to be the main underlying feature. "However, the association between ABCB1-rs1045642 polymorphism and mood disorders has not been established." (PMID 36698099, 2023).
mycoplasma infection (1 paper, 2017). "However, we did not detect any changes in expression or sub-cellular locations of ABCB1, ABCC1 and ABCG2, suggesting that mycoplasma infection alters neither the quantity of ABC transporters nor their functional proportions on cell membrane." (PMID 28976984, 2017).
myelodysplastic syndrome (1 paper, 2021). A clonal hematopoietic disorder characterized by dysplasia and ineffective hematopoiesis in one or more of the hematopoietic cell lines. "Here, we proved that latrophilin-1 expression also occurs in the myeloid blasts of patients newly diagnosed with myelodysplastic syndrome when ABCB1 is overexpressed." (PMID 34298843, 2021). "In the present work, we demonstrated such a reciprocal relationship between ABCB1 and latrophilin-1 expression in samples of patients newly diagnosed with myelodysplastic syndrome without prior treatment." (PMID 34298843, 2021).
Nausea (1 paper, 2021). A sensation of unease in the stomach together with an urge to vomit. "The objective for this study was to investigate whether MTX-induced nausea was associated with selected SNPs in candidate genes encoding MTX transporter proteins (SLCO1B1, SLCO1B3, SLC19A1, ABCB1, ABCC2), the MTHFR enzyme (MTHFR) and the 5-HT3-receptor (HTR3A, HTR3B), in children with JIA." (PMID 33794950, 2021).
neuroepithelial tumors (1 paper, 2014). "The major mechanism of drug resistance in GBM is the over-expression of the multi-drug resistance protein (MDR-1; p-glycoprotein 1 or ABCB1), seen in the BBB and neuroepithelial tumors such as GBM." (PMID 24433351, 2014).
Norrie disease (1 paper, 2024). A rare X-linked genetic vitreoretinal condition characterized by abnormal retinal development with congenital blindness. "Identification of substrates of the human orthologue ABCB1 could help minimize ototoxicity in individuals with Norrie disease." (PMID 39585982, 2024).
oral mucositis (1 paper, 2017). Inflammation of the mucous membranes of any of the structures in the mouth. "Compared with patients with the TT genotype, those with the ABCB1 rs1128503C allele had a higher risk of developing oral mucositis after receiving HDMTX (P = 0.054)), and had a longer duration of hospitalization for the HDMTX treatment (P = 0.006)." (PMID 28525903, 2017).
pemphigoid (1 paper, 2018). "In available literature, one can find papers on the role of ABCB1 polymorphisms in dermatologic diseases with an autoimmune background, which pemphigoid is classified as." (PMID 29948283, 2018).
peripheral artery-disease (1 paper, 2025). "New trending topics are related to ABCB1, peripheral artery disease, direct-acting oral anticoagulants, PCI, and SARS-CoV-2." (PMID 41148788, 2025). "New trending topics are related to ABCB1, peripheral artery disease, direct-acting oral anticoagulant, PCI, and SARS-CoV-2." (PMID 41148788, 2025). "The new keywords that appeared in the 2021–2024 time range were “ABCB1” (13 times), “peripheral artery-disease” (12 times), “direct-acting oral anticoagulant” (7 times), “PCI” (10 times), and “SARS-CoV-2” (10 times)." (PMID 41148788, 2025).
Pf (1 paper, 2017). "Therefore, it is conceivable that higher expression of ABCB1 in lymphocytes of Pf subjects is due to the enhanced cytokine expression and that it acts to promote efflux of compounds such as bilirubin or antimalarial drug to facilitate its survival." (PMID 28422980, 2017).
preeclampsia (1 paper, 2022). Preeclampsia is a hypertensive disorder of pregnancy that is characterized by new-onset hypertension with proteinuria presenting after 20 weeks of gestation, and depending on mild or severe forms may initially present with severe headache, visual disturbances, and hyperreflexia. "Moreover, it has been indicated that a decrease in ABCB1 activity in syncytial and extravillous trophoblast may play an important role in severe preeclampsia." (PMID 36013052, 2022).
primary progressive MS (1 paper, 2020). "In retrospective analyses, association of SNPs in ABCB1 and ABCG2 genes with drug effects has been shown at least for relapsing and secondary progressive MS but not for primary progressive MS." (PMID 31915017, 2020).
pulmonary TB (1 paper, 2023). "P-glycoprotein (encoded by the ABCB1 gene) has a dual role in regulating inflammation and reducing chemotherapy efficacy in various diseases, but there are few studies focused on pulmonary TB patients." (PMID 37834286, 2023). "In this study, our objective was to identify a list of genes that correlate with high and low levels of ABCB1 gene expression in the lungs of pulmonary TB patients with different activity of chronic granulomatous inflammation." (PMID 37834286, 2023).
renal papillary cell carcinoma (1 paper, 2020). "Taken together, these data indicated ABCB1 exonic stability is cancer cell type-specific (e.g., in both AMLs and renal papillary cell carcinoma)." (PMID 34541464, 2020).
sarcopenia (1 paper, 2026). Progressive decline in muscle mass due to aging which results in decreased functional capacity of muscles. "Our findings reveal a novel "bile acid-MMEC-muscle" axis in sarcopenia, where miR-135a-5p-mediated ABCB1 downregulation in MMECs disrupts the local bile acid milieu and impairs muscle regeneration, highlighting ABCB1 as a potential therapeutic target for aging-related muscle loss." (PMID 41898511, 2026).